SDC1 (syndecan 1)
Description:
Cell surface proteoglycan that contains both heparan sulfate and chondroitin sulfate and that links the cytoskeleton to the interstitial matrix (By similarity). Regulates exosome biogenesis in concert with SDCBP and PDCD6IP. Able to induce its own expression in dental mesenchymal cells and also in the neighboring dental epithelial cells via an MSX1-mediated pathway (By similarity).
Synonyms: SYND1; CD138; SDC; syndecan
Tractability: Small molecule: a structure with a bound ligand is known. Antibody: UniProt places it where antibodies can reach, with high confidence; its Gene Ontology location is reachable by antibodies, with high confidence; UniProt predicts a signal peptide or a membrane-spanning region. PROTAC: ubiquitination databases record sites on it; its protein half-life has been measured. Other modalities: a drug acting on it is in phase 2 or 3 trials.
Gene: Protein-coding gene on chromosome 2 (20,200,796 to 20,225,433, reverse strand). Ensembl gene ENSG00000115884.
Subcellular location: Membrane; Secreted; Secreted, extracellular exosome
Subcellular location (Human Protein Atlas): Focal adhesion sites; Predicted to be secreted
Pathways (Reactome):
Disease: Attachment and Entry; Defective B3GALT6 causes EDSP2 and SEMDJL1; Defective B3GAT3 causes JDSSDHD; Defective B4GALT7 causes EDS, progeroid type; Defective EXT1 causes exostoses 1, TRPS2 and CHDS; Defective EXT2 causes exostoses 2; Dengue Virus Attachment and Entry; Dengue Virus-Host Interactions; RSV-host interactions; Respiratory syncytial virus (RSV) attachment and entry
Hemostasis: Cell surface interactions at the vascular wall; Initiation of coagulation cascade; Regulation of clotting cascade
Metabolism: Glycosaminoglycan-protein linkage region biosynthesis; HS-GAG biosynthesis; HS-GAG degradation
Extracellular matrix organization: Syndecan interactions
Immune System: Other interleukin signaling
Sensory Perception: Retinoid metabolism and transport
Gene Ontology:
Molecular function: identical protein binding; protein binding; cargo receptor activity
Biological process: positive regulation of exosomal secretion; positive regulation of extracellular exosome assembly; striated muscle cell development; myoblast development; receptor-mediated endocytosis
Cellular component: cell surface; extracellular exosome; extracellular region; Golgi lumen; lysosomal lumen; plasma membrane; external side of plasma membrane; membrane
Genetic constraint (gnomAD): Loss-of-function variants: 14 observed, 24.89 expected, observed/expected ratio (o/e) 0.56, 90% interval 0.37 to 0.88. The upper end of that interval is the gene's LOEUF score, 0.88, which puts it in group 3 of 6, group 1 being the genes least tolerant of losing a copy. Missense variants: 405 observed, 390.65 expected, observed/expected ratio (o/e) 1.04, 90% interval 0.95 to 1.13. Synonymous variants: 204 observed, 167.82 expected, observed/expected ratio (o/e) 1.22, 90% interval 1.08 to 1.37.
Homologues: Orthologues: chimpanzee SDC1 (99% identical), macaque SDC1 (81% identical), dog SDC1 (81% identical), mouse Sdc1 (77% identical), pig SDC1 (77% identical), rabbit SDC1 (75% identical), rat Sdc1 (71% identical), guinea pig SDC1 (64% identical), tropical clawed frog sdc1 (39% identical), Drosophila melanogaster Sdc (26% identical), Caenorhabditis elegans sdn-1 (19% identical). Paralogues in human: SDC3 (35% identical), SDC2 (21% identical), SDC4 (19% identical).
Diseases named in the same sentence as SDC1 in open-access papers:
SDC1 is named in the same sentence as 478 diseases in open-access papers, as found by Europe PMC text mining. Sharing a sentence is not in itself a finding about the gene and the disease. The quoted sentences say what the papers report.
myeloma (520 papers, 2006 to 2026). "Aside from autoimmune diseases, elevated levels of SDC-1 in serum have been associated with conditions that involve the expansion and activation of plasma cells, such as multiple myeloma." (PMID 39509329, 2025). "High levels of cell surface syndecan-1 expression are a hallmark of myeloma tumors, with the HS chains of this protein being crucial for MM cell proliferation and survival in the BM microenvironment." (PMID 38540127, 2024). "In breast cancer, multiple myeloma and pancreatic cancer, greater SDC-1 shedding was similarly found to associate with increased metastasis, indicating that shed SDC-1 likely serves as a major facilitator for malignant cellular invasion." (PMID 35118073, 2021). "Cell staining demonstrates that shed Sdc1 causes VLA-4 to re-localize from the lagging edge to the leading edge of myeloma cells where it localizes with the shed Sdc1 and VEGFR2 when cells are plated on VLA-4 ligands." (PMID 34778093, 2021). "VEGFR2 has been shown previously to associate with Sdc1 in myeloma-derived vascular endothelial cells." (PMID 34778093, 2021). "SDC1 expression level is also associated with responses to chemotherapy and with prognosis in multiple solid and hematological cancers, including multiple myeloma and Hodgkin lymphoma." (PMID 26293675, 2015). "Syndecan-1 is the main diagnostic and prognostic marker of myeloma, and its importance for hematological malignancies was recently reviewed." (PMID 26420915, 2015). "This association between syndecan-1 and αvβ3 and αvβ5 integrins was described for carcinomas, myeloma, fibroblasts, and activated vascular endothelial cells." (PMID 26420915, 2015). "In multiple myeloma, soluble SDC1 levels were found to be directly associated with the progression of disease, and therefore this association should be evaluated in other cancers as well." (PMID 26293675, 2015). "Of note, the proteasomal inhibitor bortezomib, which is used in the clinic to prevent transcription factor activation (e.g. NF- κB) in multiple myeloma cells, causes the accumulation of the syndecan-1 cCTF in tumor cells." (PMID 26378057, 2015). "Syndecan-1 is used as a standard diagnostic biomarker in multiple myeloma and it is highly expressed in various human cancers comprising pancreatic and breast cancer." (PMID 24392351, 2013). "Furthermore, increased soluble syndecan-1 (CD138) levels, which are associated with myeloma cells, have been linked to poor prognoses." (PMID 38900304, 2024). "In addition, significant associations between circulating SDC1 and the outcome of patients with other tumor entities including lung cancer, prostate cancer, bladder cancer, and multiple myeloma have been reported in the literature." (PMID 36353562, 2022). "Sdc1 is highly expressed on malignant plasma cells and has a causal role in multiple myeloma." (PMID 26926788, 2016). "Importantly, single-cell analysis of a patient with relapsed/refractory MM confirmed these observations by showing a strong induction of DDIT3 and a concomitant SDC1 reduction, associated with a reduction of the myeloma fraction by >50% after 24 h of NCP26 exposure." (PMID 36631435, 2023). "In fact, clonogenic Syndecan-1/CD138− myeloma cells exhibit stemness traits and tumour-initiating properties that are normally associated with poorer prognosis." (PMID 39980017, 2025). "For example, it has been shown that both healthy PCs and malignant myeloma cells exclusively express the plasma cell marker Syndecan-1 (CD138)." (PMID 40977723, 2025). "Targeting CD138 (syndecan-1), a transmembrane proteoglycan highly expressed in myeloma cells and certain epithelial cells, has emerged as a therapeutic strategy, including using a drug-conjugated anti-CD138 antibody (BT026)." (PMID 40124378, 2025). "BCMA is essential for plasma cell survival and is targeted in multiple myeloma therapies, while CD138 (Syndecan-1) and CD38 are also key plasma cell markers." (PMID 40482292, 2025).
myeloma (continued). "Because syndecan-1 has been shown to be the predominant HS proteoglycan expressed by most myeloma cells, we performed FACS analysis of cell surface syndecan-1." (PMID 38265424, 2024). "For example, SDC1 has long been established to be prominently expressed by multiple myeloma plasma cells." (PMID 38912739, 2024). "CD138, also called syndecan-1, is a surface protein found on the surfaces of plasma and myeloma cells." (PMID 38006053, 2023). "Similar to previous work, we observed a reduction in the abundance of SDC1, which is an essential survival factor for myeloma that regulates its BM localisation and microenvironment interactions." (PMID 36631435, 2023). "It has been proposed that CD138 (syndecan-1) promotes the survival of mature PCs, as well as multiple myeloma cells, by binding of anti-apoptotic factors, growth factors, and pro-survival cytokines, such as APRIL, or IL-6 through its heparan sulfate moieties." (PMID 37174629, 2023). "Heparanase leads to structural modifications of syndecan-1 resulting in syndecan-1 shedding from the myeloma cell surface." (PMID 36980254, 2023). "Our report expands previous observations pointing to the role of syndecan-1 in the complex reciprocal interaction between multiple myeloma cells and their bone marrow niche." (PMID 36088392, 2023). "SDC1, a type I single transmembrane proteoglycans, can be dysregulated in many types of tumors including multiple myeloma, breast cancers, prostate carcinomas, colon cancer, and pancreatic cancer." (PMID 37441590, 2023). "Targeting CAMs such as CD38 and CD138/SDC1 with monoclonal antibodies have achieved promising results in multiple myeloma." (PMID 36522654, 2022). "Comparison of myeloma cells to the two B-lymphoblastoid cell lines also showed CD138/SDC1 and CD28 as characterizing myeloma cells, while CD19, CD22, and CD20 characterized late-stage B-cells." (PMID 35840578, 2022). "Recent works characterizing MM CTCs have focused on the surface marker CD138 (syndecan-1) for identification and isolation and have provided significant insights into the nature and role of these cells in myeloma." (PMID 35621632, 2022). "al. showed that MM cells can bind to a considerable quantity of APRIL and soluble TACI via cell surface syndecan-1 which this binding to syndecan-1 is essential for APRIL myeloma cell growth and survival." (PMID 35144648, 2022). "Myeloma patients with advanced disease are known to express high levels of heparanase and to have high levels of shed Sdc1 in the tumor microenviroment and the blood." (PMID 34778093, 2021). "Myeloma tumors are characterized by high levels of expression of cell surface syndecan-1, with its HS chains playing the most important role for the growth of MM cell and survival within the BM microenvironment." (PMID 33842343, 2021). "Syndecan-1, SDC1, is a transmembrane protein that is highly expressed in various cancer types and is required for cell invasion and proliferation in myeloma and glioma cells." (PMID 33567514, 2021). "In the human myeloma cell, intranuclear SDC-1 interacts with the enzyme histone acetyltransferase p300 (HAT) via HS chains to decrease its activity and thus histone acetylation." (PMID 35118073, 2021). "This is in agreement with the notion that Sdc-1 knockdown myeloma cells formed fewer and smaller tumors exhibiting diminished levels of VEGF and impaired development of blood vessels in mice." (PMID 34066023, 2021). "In particular, Indatuximab ravtansine (BT062), an antibody-drug conjugate that binds to syndecan-1, has recently been successfully used in clinical trials in patients with relapsed multiple myeloma, stabilizing or improving disease in almost 80% of patients." (PMID 33669066, 2021). "For example, in heparinase-induced shedding by myeloma cells, the soluble syndecan-1 promotes endothelial cell invasion and angiogenesis." (PMID 33669066, 2021).
myeloma (continued). "Commonly used chemotherapy and radiation regimens promote heparanase upregulation and increase SDC-1 shedding in malignancies such as myeloma, pancreatic cancer and medulloblastoma." (PMID 35118073, 2021). "SDC1, also known as CD138, is overexpressed on malignant plasma cells and for 25 years has been used as a primary diagnostic marker for multiple myeloma." (PMID 34249755, 2021). "Syndecan-1's HS chains promote cell proliferation by directly binding Wnt3a and activating paracrine Wnt-Fzd signalling in multiple myeloma." (PMID 33561383, 2021). "Single mAbs or drug-conjugated antibodies targeting SDC1 have been successfully used in melanoma, triple negative breast cancer and multiple myeloma treatment in vitro and in vivo studies." (PMID 33990545, 2021). "Antibody-targeting of SDC1 has been used alone or combined with chemotherapy to treat multiple myeloma, and a clinical trial using CAR-T cells recognising SDC1 suggests that the treatment is safe, well-tolerable and has potential antitumour activity." (PMID 33494442, 2021). "Specifically, TNFSF13B expression had close interactions with macrophage marker genes, namely, TLR and S100A9 genes; their receptor genes, TNFRSF13B and TNFRSF17, showed significant associations with the myeloma-related genes CD38, SDC1, and MYEOV." (PMID 34150664, 2021). "CD138 (or syndecan-1) is expressed on normal and malignant plasma cells and therefore seems to be a reliable target for multiple myeloma." (PMID 34572927, 2021). "As referred earlier, SDC1 overexpression in multiple myeloma was also shown to promote angiogenesis by its ability to physically interact with VEGFR2 and prevent the receptor recycling." (PMID 33494442, 2021). "Clinical drugs used for myeloma showed to induce SDC1 shedding, due to the upregulation of HPSE expression." (PMID 33494442, 2021). "Myeloma cells exposed to elevated heparanase levels exhibited increased secretion of exosomes containing SDC-1 and heparanase." (PMID 35118073, 2021). "FACS analyses revealed that U266 cells express the highest levels of syndecan-1, as would be expected for myeloma cells, whereas U87 cells express high levels of syndecan-4." (PMID 33585253, 2020). "For example, in myeloma, shed SDC1 promotes HGF paracrine signaling that involves MAPK and PI3K cascade activation resulting in enhanced cell proliferation and survival." (PMID 32916872, 2020). "Myeloma cells also produce heparanase, an enzyme that cleaves heparanase sulfate chains of adhesive proteoglycans such as syndecan-1." (PMID 33634031, 2020). "Consistently, heparanase, by enhancing MMP-9 expression, induces expression and shedding of Sdc-1 in myeloma and BC." (PMID 32604738, 2020). "The chosen targeted antigen is CD138, also called syndecan-1, which is a proteoglycan expressed on epithelial cells and broadly overexpressed on the extracellular membrane of myeloma cells." (PMID 32971984, 2020). "Ramani and Sanderson observed that myeloma patients with higher expression of syndecan-1 on the cell surface were chemoresistant." (PMID 32983743, 2020). "The knockdown of SDC1 in myeloma cells resulted in smaller and fewer tumor formation subcutaneously or intravenously, with impaired development of blood vessels." (PMID 32756007, 2020). "SDC1 represents the dominant HS expressed on the surface of multiple myeloma cells and regulates cell growth and survival." (PMID 32575635, 2020). "The interaction of the extracellular domain of SDC1 with αvβ3 and αvβ5 integrins regulates angiogenesis and tumorigenesis in human mammary carcinoma cells, and myeloma." (PMID 32916872, 2020). "In myeloma, SDC1-mediated activation of the VEGF receptor on adjacent endothelial cells promotes AKT and ERK signaling and stimulates tumor angiogenesis." (PMID 32916872, 2020). "Increased SDC1 serum levels were demonstrated in various tumors, such as myeloma, breast cancer, and colon carcinoma." (PMID 33114033, 2020).
myeloma (continued). "Syndecan-1 activated by high levels of heparanase in MM cells promotes the spontaneous metastasis of myeloma cells to the bone." (PMID 31266187, 2019). "In breast cancer and multiple myeloma, syndecan-1 overexpression correlates with aggressive phenotype and poor prognosis and was implicated in resistance to either cytotoxic or targeted therapeutics." (PMID 30413079, 2018). "Cell surface proteoglycan syndecan-1 (CD138) is highly expressed in multiple myeloma cells and function as a coreceptor for HGF that promotes HGF/Met signaling in MM cells." (PMID 30237983, 2018). "This is due to the fact that the reduced adherence of syndecan-1 knocks multiple myeloma endothelial cells (MMECs) to Matrigel." (PMID 30135409, 2018). "Syndecan-1 ectodomain purified from multiple myeloma cells significantly inhibited osteoclast differentiation at picomolar concentrations." (PMID 30389911, 2018). "Syndecan-1 in lymphoblastoid B cells or Multiple myeloma (MM) cells was reported to promote cell adhesion." (PMID 30135409, 2018). "SDC1 (CD138) is used as a marker for plasma cells, and myeloma cells and several carcinomas, such as breast cancer cells, express high levels of SDC1." (PMID 30373658, 2018). "After stimulation with SCGB3A2, the SDC1 signal became relatively concentrated on cell protrusions equivalent to the uropod structure of myeloma, which co-localized with SCGB3A2 (+SCGB3A2)." (PMID 30526845, 2018). "An additional form of cooperation between heparanase and syndecan-1 in the regulation of exosome biogenesis was first reported by the group of Sanderson in a study performed using multiple myeloma cell models with high and low heparanase expression." (PMID 30413079, 2018). "Jung and collaborators demonstrated that a syndecan-1 juxtamembrane site, exposed upon shedding in endothelial and myeloma cells, binds both VEGF receptor 2 (VEGFR2) and very late antigen 4 (VLA-4)." (PMID 30413079, 2018). "Clinical anti-myeloma drugs were shown to induce syndecan-1 shedding in multiple myeloma cell cultures and in tumor xenografted mice, as well as the upregulation of heparanase expression and its release into conditioned medium." (PMID 30413079, 2018). "In multiple myeloma models, heparanase was found to represent a critical factor regulating levels of HS and syndecan-1 in the nucleus." (PMID 30413079, 2018). "Syndecan 1 (CD138) on myeloma cells binds HGF and promotes c-MET signaling, while both potentiate interleukin-6-induced growth and migration, correlating with shorter survival." (PMID 28337527, 2017). "Highly expressed on neoplastic plasma cells, syndecan-1 has shown to be a viable target for myeloma therapy." (PMID 28399903, 2017). "In myeloma syndecan-1 inhibited apoptosis while its knock-down resulted in increase of apoptosis in endometrial cells, myeloma and urothelial carcinoma cells." (PMID 29216821, 2017). "This conforms with the observation that CD138/Syndecan-1(+) multiple myeloma cells express Hedgehog genes and that inhibition of Smoothened decreased multiple myeloma cell viability by downregulating Gli-1 and Patched1." (PMID 28270211, 2017). "Together this demonstrates TM-derived exosomes bind fibronectin through a mechanism similar to but distinctly different than the syndecan-1-mediated mechanism used by myeloma cell-derived exosomes." (PMID 27783649, 2016). "Collectively, our findings reveal for the first time the mechanism through which HPSE modulates Sdc1 function to promote both tumor cell invasion and angiogenesis, thereby driving multiple myeloma progression." (PMID 26926788, 2016). "In a comparative study of blood dyscrasias, multiple myeloma patients showed higher serum SDC1 levels than patients with plasmocytoma or monoclonal gammopathy." (PMID 26293675, 2015). "Most importantly, high serum levels of syndecan-1 reflect a high tumor burden and predict poor prognosis in myeloma patients." (PMID 25686828, 2015).